KLF2P1 (KLF2 pseudogene 1)
Gene: Transcribed processed pseudogene on chromosome 2 (130,036,958 to 130,038,422, forward strand). Ensembl gene ENSG00000231240.
Diseases named in the same sentence as KLF2P1 in open-access papers:
KLF2P1 is named in the same sentence as 1 disease in open-access papers, as found by Europe PMC text mining. Sharing a sentence is not in itself a finding about the gene and the disease.
KLF2P1 shares sentences with these, for which no sentence is quoted: endometriosis (1 paper).